ABCA2 (ATP binding cassette subfamily A member 2)
Description:
Probable lipid transporter that modulates cholesterol sequestration in the late endosome/lysosome by regulating the intracellular sphingolipid metabolism, in turn participates in cholesterol homeostasis (Probable). May alter the transbilayer distribution of ceramide in the intraluminal membrane lipid bilayer, favoring its retention in the outer leaflet that results in increased acid ceramidase activity in the late endosome/lysosome, facilitating ceramide deacylation to sphingosine leading to the sequestration of free cholesterol in lysosomes. In addition regulates amyloid-beta production either by activating a signaling pathway that regulates amyloid precursor protein transcription through the modulation of sphingolipid metabolism or through its role in gamma-secretase processing of APP. May play a role in myelin formation (By similarity).
Synonyms: ABC2; IDPOGSA
Tractability: Small molecule: it belongs to a druggable protein family. Antibody: UniProt places it where antibodies can reach, with high confidence; its Gene Ontology location is reachable by antibodies, with high confidence; UniProt predicts a signal peptide or a membrane-spanning region. PROTAC: ubiquitination databases record sites on it; its protein half-life has been measured.
Gene: Protein-coding gene on chromosome 9 (137,007,234 to 137,028,915, reverse strand). Ensembl gene ENSG00000107331.
Subcellular location: Endosome membrane; Lysosome membrane
Subcellular location (Human Protein Atlas): Vesicles
Pathways (Reactome):
Transport of small molecules: ABC transporters in lipid homeostasis
Gene Ontology:
Molecular function: ATP binding; ceramide floppase activity; endopeptidase regulator activity; protein binding; ATPase-coupled transmembrane transporter activity; nucleotide binding; ABC-type transporter activity; ATP hydrolysis activity; floppase activity
Biological process: ceramide translocation; cholesterol homeostasis; intracellular sphingolipid homeostasis; negative regulation of cholesterol efflux; negative regulation of intracellular cholesterol transport; negative regulation of phospholipid biosynthetic process; negative regulation of receptor-mediated endocytosis involved in cholesterol transport; negative regulation of sphingolipid biosynthetic process; positive regulation of amyloid precursor protein biosynthetic process; positive regulation of amyloid precursor protein catabolic process; positive regulation of amyloid-beta formation; positive regulation of low-density lipoprotein particle receptor catabolic process; regulation of cholesterol biosynthetic process; regulation of intracellular cholesterol transport; regulation of post-translational protein modification; regulation of steroid metabolic process; response to cholesterol; response to steroid hormone; sphingosine biosynthetic process; central nervous system myelin formation; ganglioside metabolic process; glycosphingolipid metabolic process; lipid metabolic process; locomotory behavior; negative regulation of steroid metabolic process; and 7 more
Cellular component: endosome; endosome membrane; lysosomal membrane; lysosome; membrane; plasma membrane; ATP-binding cassette (ABC) transporter complex; cytoplasmic vesicle; microtubule organizing center
Genetic constraint (gnomAD): Loss-of-function variants: 83 observed, 228.66 expected, observed/expected ratio (o/e) 0.36, 90% interval 0.3 to 0.44. The synonymous counts are far from expectation, so gnomAD's model fits this gene poorly and the ratio says little. Missense variants: 2,656 observed, 3,239.5 expected, observed/expected ratio (o/e) 0.82, 90% interval 0.79 to 0.85. Synonymous variants: 1,696 observed, 1,431.7 expected, observed/expected ratio (o/e) 1.18, 90% interval 1.14 to 1.23.
Homologues: Orthologues: macaque ABCA2 (99% identical), pig ABCA2 (94% identical), mouse Abca2 (93% identical), guinea pig ABCA2 (93% identical), rat Abca2 (93% identical), chimpanzee ABCA2 (89% identical), tropical clawed frog abca2 (77% identical), zebrafish abca2 (77% identical), Caenorhabditis elegans abt-2 (24% identical), Caenorhabditis elegans abt-4 (22% identical), Drosophila melanogaster Abca3 (22% identical), Drosophila melanogaster CG6052 (20% identical), and 8 more. Paralogues in human: ABCA1 (39% identical), ABCA4 (36% identical), ABCA7 (34% identical), ABCA12 (28% identical), ABCA13 (28% identical), ABCA3 (25% identical), ABCA5 (18% identical), ABCA9 (17% identical), ABCA8 (17% identical), ABCA6 (16% identical), ABCA10 (16% identical).